SOX2 (SRY-box transcription factor 2)
Diseases named in the same sentence as SOX2 in open-access papers (continued):
Sharing a sentence is not in itself a finding about the gene and the disease.
tumor (continued). "Stainings for several stemness related markers revealed a significant decrease of SOX2 staining intensity in SB747651A exposed tumor spheroids (mean intensity 149.5 arbitrary units) vs. controls (mean intensity 187.4) (P = 0.02)." (PMID 33727611, 2021). "As predicted, the results showed that the expression of Sox2 was upregulated with the decrease of tumor differentiation degree, whereas CK18 expression displayed the opposite trend, as revealed by immunohistochemistry." (PMID 33649532, 2021). "Phenotypically, SFRP2 decreased tumor sphere formation, stemness as assessed by limiting dilution assay, and overall cell proliferation but increased cell motility, whereas SOX2 induced the opposite effects." (PMID 34021259, 2021). "Their expression pattern correlates with the progenitor marker SOX2 and the proliferation status of tumorous epithelial cells; however, the distribution of positive cells is distinct in these two neoplasms." (PMID 34072517, 2021). "Our recent studies have shown that elevating SOX2 from an inducible promoter in a wide range of human tumor cell lines, including the SHH MB cell lines, can lead to a dramatic reduction of proliferation both in vitro and in vivo." (PMID 35054230, 2021). "Meeting the major challenge of tumor recurrence for SHH MB will require targeting the stem cell population of SOX2+ cells." (PMID 35054230, 2021). "Our results indicated the overexpression of SOX2 in HCC tumor tissues compared to normal tissues, and that was correlated with clinical stage and histological grade which confirms the role of CSCs in the development of HCC." (PMID 34436030, 2021). "SOX2 is required for tumor cells to retain the characteristics of CSCs such as being highly tumorigenic and metastatic." (PMID 33499351, 2021). "This study aimed to determine the prognostic value of SOX2 in tumor progression and survival rate of patients with HCC." (PMID 34436030, 2021). "SOX2 amplification in tumour cells leads to an increased autophagic influx, which promoted the turnover of STING in HNSCC cells." (PMID 33605033, 2021). "A similar differentiation pattern was also found in patient tissue, where only few SOX2+ tumour cells upregulated SOX10 in intact myelin." (PMID 33846316, 2021). "The unsupervised t-distributed stochastic neighbor embedding (tSNE) clustering of the scATAC-seq resulted in multiple clusters that we analyzed for differential accessibility at SOX2 promoter to distinguish tumor and normal cells." (PMID 34599169, 2021). "There is evidence that Sox2-positive SiHa and C33A cells, as compared to Sox2-negative cells, demonstrate more pronounced abilities for self-renewal, differentiation, and tumor formation." (PMID 34830452, 2021). "By emerging CRISPR-Cas9 genome editing technology, several research lines have been established to better understand the importance of SOX2 in cell differentiation, the acquisition of stem characteristics, and tumor progression." (PMID 34768751, 2021). "Further studies with higher numbers of study subjects are therefore necessary to determine the correlation between SOX2 expression and tumor progression in HCC." (PMID 34436030, 2021). "We used the SOX2 transcription factor to and transdifferentiation media to convert fibroblasts into tumor‐homing iNSCs." (PMID 33532581, 2021). "Although, at mRNA level, CCND1 expression wassignificantly lower in tumor samples (P<0.001), SOX2, BRAF,TNFA, and VEGF expression was increased in malignant tissuescompared with normal adjacent samples (P<0.05)." (PMID 34308569, 2021). "Sox-2 mediated upregulation of BIRC5 is important in tumour progression, apoptotic inhibition, and resistance to chemotherapy in cancers." (PMID 34685742, 2021).
tumor (continued). "sox2 is a typical marker of poor differentiated cells that have been associated with CSC and tumor aggressiveness whose levels are regulated by several pathways including EGFR." (PMID 34012924, 2021). "The data presented here clearly show that CDK9 inhibitors suppress the expression of Sox2 and Sox9, and interfere with anchorage independent growth of tumor cells." (PMID 34359807, 2021). "Recent study found that the Sox2 gene can regulate the motility of colorectal cancer cells and promote tumor progression through the Rho-ROCK signaling pathway." (PMID 33588867, 2021). "The early-stage human 3D organoid was also a relevant in vitro model suggesting virus preference to tumor cell even co-cultured with SOX2+ normal cells." (PMID 34696533, 2021). "Several studies reported overexpression of SOX2 in GSC subpopulations and in patient samples, and the high levels are associated with tumor aggressiveness and worse prognosis." (PMID 33805518, 2021). "Fluspirilene inhibited STAT3, resulting in decreased GBM proliferation, invasion and tumor growth, penfluridol decreased colony sphere number and size with reductions in (sex determining region Y)-box 2 (SOX2) and octamer-binding transcription factor 4 (OCT4)." (PMID 33919596, 2021). "Consistent with the results from PHB deletion in GSC-derived xenografts, RocA treatment resulted in a dramatic increase in ROS levels, a reduction in SOX2+ tumor cells, and an increase in cell death in tumors." (PMID 34140524, 2021). "SOX2 plays a vital role in tumor development, progression, and cell survival in various cancer types." (PMID 33789601, 2021). "These melanoma tumor‐repopulating cells express high levels of self‐renewing gene Sox2 and exhibit a very low intrinsic cell stiffness of ~0.5 kPa." (PMID 33754478, 2021). "In conclusion, this study revealed that MYC-induced transformation of Sox2+/Aldh1a1high cells led to tumour growth in the postnatal cerebellum in vivo, with characteristics of type 3 medulloblastoma." (PMID 34445233, 2021). "Herein, it was shown that actinomycin D targets Sox-2, a stem cell transcription factor, and downregulates its expression resulting in a reduction of stem-cell population and stalling of the tumor progression initiation." (PMID 34884835, 2021). "SOX2, OCT4, and NANOG are CSC markers associated with tumor proliferation and tumor differentiation." (PMID 34803458, 2021). "The overexpression of Oct4 and Sox2 influences not only the differentiation of mesenchymal stem cells but also the tumor-initiating capacity of CSCs." (PMID 34349823, 2021). "It is rational to slow down proliferation triggered by SOX2 to promote tumour dormancy, yet how these factors interact with each other during dormancy is unclear." (PMID 34539663, 2021). "In agreement with our PDX samples, we found that tumor tissue cores from patients with CR possessed higher caveolin-1 positivity and lower Sox-2 positivity than those from patients with PD." (PMID 34546978, 2021). "Chromatin immunoprecipitation-RNA sequencing analyses on a set of murine LUSC and LUAD tumours, suggested that SOX2 and NKX2-1 exert antagonistic effects on the regulation of Cxcl5 expression." (PMID 34354223, 2021). "Ki-67 and Sox-2 were found to exhibit high expression in the nuclei and cytoplasm of the tumor cells in this study." (PMID 34712723, 2021). "IHC staining revealed that αPD-L1 Ab in combination with NPs-Stattic-IL20RA inhibited the expression of p-STAT3 (Tyr705) and SOX2 in tumor tissues compared with IgG, αPD-L1 Ab, NPs-Stattic, and NP-Stattic-IL20RA plus IgG treatment, respectively." (PMID 33456560, 2021). "The inhibitory function of finasteride in the maintenance of the stemness was confirmed by qRT-PCR, showing that the mRNA level of Sox2, a marker for stem-like tumor cells, was downregulated by finasteride treatment." (PMID 34575486, 2021).
tumor (continued). "These inhibitors suppressed the expression of several genes like Sox2, Sox9, and Mcl1 that promote tumor growth, facilitating growth arrest." (PMID 34359807, 2021). "The HH pathway has been shown to regulate the properties of CSCs in various neoplasms through the up-regulation of stemness-related genes (Nanog, Oct4, Sox2 and Bmi1)." (PMID 34354950, 2021). "One approach to addressing this daunting challenge is to identify the vulnerabilities of the population of infrequently proliferating SOX2+ tumor cells." (PMID 35054230, 2021). "Some cells in the tumor also demonstrated nuclear immunoreactivity for the immature/dedifferentiated Schwann cell marker Sox2 (20–40% positivity)." (PMID 33707600, 2021). "Further, this modification is coupled with the MEK1 kinase activity to activate ERK1/2 phosphorylation, leading to the upregulated expression of IGF2BP1 and its downstream target SOX2 and thus driving EC tumor progress." (PMID 33747724, 2021). "Correlations with immune profiles CD4+, CD8+, and FOXP3+ tumor-infiltrating lymphocytes (TILs), tumoral PD-L1, and stem-related factors NANOG and SOX2 were assessed, and also associations with clinical data and patient survival." (PMID 33494389, 2021). "Although SOX2 expression increases the stemness degree of tumor cells, little is known about the expression pattern of SOX2 in HCC." (PMID 34436030, 2021). "For example, combined treatment with pentafluridol and temozolomide significantly inhibited tumor growth, while reducing the expression of Sox2 and Oct4 as well as the expression of EMT factors." (PMID 33788424, 2021). "An important mechanism that links Sox2 activity with CSCs is its role in regulating the tumor suppressive Hippo pathway." (PMID 34201496, 2021). "Among sarcomas, the role of SOX2 in tumor initiation and progression has been well characterized in osteosarcoma." (PMID 33804155, 2021). "Western blot analysis revealed that the levels of Gli1, BMI1, and SOX2 proteins in the tumor tissues from GANT61-treated mice were significantly lower than that from untreated controls." (PMID 33499351, 2021). "In conclusion, co-activation of Shh and Wnt signaling in Sox2- and Rax-positive retinal precursor cells at E8.5 resulted in the formation of tumor-like ocular lesions." (PMID 34785636, 2021). "Upon removal of the inducer, SOX2 levels returned to baseline and tumor growth resumed to match their uninduced counterparts." (PMID 35054230, 2021). "In NFIB-silenced and miR-212-3p restored group 3 MB cells, we noted decreased expression of stemness markers, i.e. CD133, Sox2, Oct4, Nanog, and β-catenin, concurrent with reduced tumor cell self-renewal capacity as evidenced by sphere-forming assays." (PMID 34922631, 2021). "Oct4, Sox2, and Nanog are recognized transcription factors mediating tumor transformation, tumorigenicity, and metastasis." (PMID 34349823, 2021). "SOX2 overexpression has indeed been co-related with tumor progression, disease recurrence and poor OS." (PMID 33823840, 2021). "mOS482 cells were successfully isolated from these tumor tissues and Sox2 was effectively knocked down using shRNA." (PMID 34201496, 2021). "In GBM, the overexpression of the ZEB1 gene induced the expression of MGMT, resulting in greater tumor chemoresistance and also induced the expression of SOX2 and OLIG2, resulting in greater stemness and higher capacity for tumor formation." (PMID 33762015, 2021). "Sex-determining region Y-box2 (SOX2), a master regulator of embryonic and induced pluripotent stem cells, drives cancer stem cells (CSCs) properties, fuels tumor initiation, and contributes to tumor aggressiveness." (PMID 33953166, 2021). "This study also revealed that Sox2 was required for tumour initiation since the co-expression of endogenous Sox2 with transduced MYC was sufficient to lead to tumourigenesis in vivo." (PMID 34445233, 2021).
tumor (continued). "More importantly, these tumor-promoting effects triggered by PAK2 overexpression were distinctly reversed by SOX2 knockdown." (PMID 34621737, 2021). "In agreement, it has been shown that SOX2 + pituitary stem cells can form tumours cell autonomously when YAP/TAZ signalling is enhanced." (PMID 34019103, 2021). "Since little is known about the expression pattern of SOX2 and apoptotic genes in HCC, we aimed to determine the prognostic significance of SOX2, Bax, and Bcl-2 in clinicopathological features, tumor progression, and survival rate of the HCC patients." (PMID 34436030, 2021). "SOX2 plays a critical role in PSCs3,6,14, in neural and other stem cell type maintenance, and in developmental and tumor biology." (PMID 33397924, 2021). "First, our evaluations revealed an increased gene expression of key molecules such as PROM1 (CD133) and SOX2 in tumor spheres derived from these cells whose role in endothelial trans-differentiation has been reported." (PMID 33396280, 2020). "Targeting SOX2+ cells in tumor masses with mithramycin, a drug that is highly effective against SOX2+ mouse and human SHH MB cells in vitro, stopped the tumor growth." (PMID 30517668, 2020). "In vivo tumor formation assay also confirmed this effect of SOX2 that mediates PRL-3's function in stem-like tumor sphere formation, indicating that SOX2 is a possible master player in PRL-3-induced expansion of CSC sub-population." (PMID 31887658, 2020). "Our studies also show that elevating SOX2 increases the expression of p27Kip1 in four out of the five tumor cell lines studied." (PMID 32998722, 2020). "Together, our findings demonstrate that downregulation of VDR in the acidic tumor microenvironment relieves the transcriptional inhibition of SOX2, resulting in increased SOX2 expression." (PMID 32900990, 2020). "De novo PITX1 expression in tumor-propagating cells controlled self-renewal and proliferation through co-binding with SOX2 and TRP63 and repressing KLF4, which maintains differentiation, in murine SCC." (PMID 33202305, 2020). "Mechanistically, SOX2 upregulation is attributed to the binding of the acetylated myocyte enhancer factor 2A (MEF2A) to SOX2 promoter in tumor cells." (PMID 31887658, 2020). "Further, we found that SOX2 was significantly overexpressed in CRC tissues compared to the paired normal tumour adjacent tissues." (PMID 33153498, 2020). "Tumor volumes and growth rates were found to have significantly decreased in tumors generated from SOX2-silenced cells." (PMID 32144236, 2020). "SOX2 overlapping transcript mainly play crucial role in tumor initiation and/or progression as well as regulating pluripotent state of stem cells." (PMID 32646427, 2020). "Here, we demonstrate the presence of an OCT4+/SOX2+/KLF4+/c-MYC+ CSC subpopulation within the tumor nests (TNs) and another within the peritumoral stroma (PTS), in this tumor." (PMID 32019273, 2020). "CSC markers including Sox2 were significantly increased in the tumor tissue compared with matched normal tissues." (PMID 32814771, 2020). "Altogether, these findings demonstrate that elevating SOX2 in multiple tumor cell lines representing three additional tumor types (androgen-independent PCa, MB and NB) inhibits cell proliferation in vitro." (PMID 32998722, 2020). "Sox2 expression in CRC is associated with several CSC features, including spheroid (3D) growth patterns, increased tumor growth and resistance to chemotherapeutic drugs, such as 5-FU." (PMID 32927726, 2020). "High endogenous SOX2 expression has also been observed in disseminated human lung tumor cells that can remain dormant for months, while retaining tumor-initiating capacity." (PMID 32998722, 2020).
tumor (continued). "On the other hand, in some studies SOX2 is thought to have a tumour suppressing action based on its reduced expression in some types of cancer, and overexpression inhibited cell proliferation and resulted in cell-cycle arrest and apoptosis." (PMID 33489519, 2020). "As hallmarks of the tumour microenvironment (TME), hypoxia and hypoxia-inducing factors (HIFs) give rise to the dysregulation of tumour stemness genes, such as SOX2." (PMID 32913192, 2020). "The essential role of Sox2 in controlling the self-renewal of tumor-initiating cells in SCC have been shown in the skin, head and neck, and lung." (PMID 32358507, 2020). "It is clear that SOX2 is a core stemness transcription factor and mediates an early step in tumour initiation." (PMID 32913192, 2020). "Collectively, our SOX2-inducible tumor studies provide a novel model system for investigating the molecular mechanisms by which elevated levels of SOX2 restrict cell proliferation." (PMID 32998722, 2020). "This led to the belief that elevation of SOX2 increases tumor cell growth both in vitro and in vivo." (PMID 32998722, 2020). "These genes act as the master regulators of cancer stem cells that play an important role of Sox-2 in tumor initiation and progression." (PMID 33080912, 2020). "Analyses of the PBI-05204–treated U87 cells revealed significant 73% declines in expression of Sox2 and a moderate reduction of other tumor stem cell markers CD44 and CXCR4." (PMID 33013390, 2020). "In our series, SOX2 expression significantly correlated with tumor grade, poor differentiation, invasive potential and poor patient survival." (PMID 32295077, 2020). "We observed significant increases in Sox2 and Notch2 expression in tumor cells isolated from obese mice compared to those from lean mice." (PMID 32098183, 2020). "In our system, tumor growth is arrested when SOX2 is elevated, yet tumor growth resumes rapidly when Dox is removed and SOX2 returns to endogenous levels." (PMID 32998722, 2020). "We also determined that elevation of SOX2 in six tumor cell lines decreased the levels of cyclins and CDKs that control each phase of the cell cycle, while upregulating p27Kip1." (PMID 32998722, 2020). "Further, PI3K/AKT inhibitor converted CSCs to differentiated tumor cells by reducing SOX2 level, thus preventing the growth of implanted resistant cells when combined with the R-CHOP regimen." (PMID 32194860, 2020). "In agreement with this, our results showed that exosomal PCAT-1 contained in CAFs triggers a CD133/SOX2-related stem cell phenotype which promotes tumor growth and guides lymph node metastasis in vivo." (PMID 32754302, 2020). "Together, these data suggest that SOX4 and SOX2 play distinct roles in tumor initiation and progression." (PMID 32427884, 2020). "For instance, the clonogenic CD138− compartment in MGUS patients expresses SOX2, an embryonal stem cell protein involved in the tumor-initiating potential and self-renewal of tumor cells." (PMID 33194767, 2020). "With univariate analysis by Cox proportional hazards model, tumor size, nodal status, grade, ER, PR, Snail and Sox2 status were demonstrated as significant prognostic parameters for DFS and OS." (PMID 32541667, 2020). "In line with the in vitro findings, napabucasin down-regulated Nanog, SOX2, Klf4 and Oct4 in the tumor cells, and also decreased the proportion of Ki67+ tumor cells." (PMID 33343368, 2020). "In contrast, during the engineering of tumor cells for stable overexpression, SOX2 is elevated during the drug selection step." (PMID 32998722, 2020). "High levels of METTL3 expression have been shown to significantly upregulate m6A methylation in the coding sequences of SOX2 mRNA, a well-known CrC marker that is involved in maintaining the properties of tumor-initiating cells." (PMID 32404927, 2020).